SLC52A2 (solute carrier family 52 member 2)
Description:
Plasma membrane transporter mediating the uptake by cells of the water soluble vitamin B2/riboflavin that plays a key role in biochemical oxidation-reduction reactions of the carbohydrate, lipid, and amino acid metabolism. Humans are unable to synthesize vitamin B2/riboflavin and must obtain it via intestinal absorption. May also act as a receptor for 4-hydroxybutyrate (Probable). (Microbial infection) In case of infection by retroviruses, acts as a cell receptor to retroviral envelopes similar to the porcine endogenous retrovirus (PERV-A).
Synonyms: hRFT3; GPR172A; PAR1; RFT3; FLJ11856; GPCR41; D15Ertd747e; RFVT2; HuPAR-1; BVVLS2
Tractability: Small molecule: a structure with a bound ligand is known. Antibody: UniProt places it where antibodies can reach, with high confidence; its Gene Ontology location is reachable by antibodies, with high confidence; UniProt predicts a signal peptide or a membrane-spanning region. PROTAC: ubiquitination databases record sites on it.
Gene: Protein-coding gene on chromosome 8 (144,333,957 to 144,361,447, forward strand). Ensembl gene ENSG00000185803.
Subcellular location: Cell membrane
Pathways (Reactome):
Metabolism: Vitamin B2 (riboflavin) metabolism
Gene Ontology:
Molecular function: 4-hydroxybutyrate receptor activity; protein binding; riboflavin transmembrane transporter activity
Biological process: riboflavin transport; riboflavin metabolic process
Cellular component: plasma membrane
Genetic constraint (gnomAD): Loss-of-function variants: 17 observed, 26.69 expected, observed/expected ratio (o/e) 0.64, 90% interval 0.44 to 0.95. The upper end of that interval is the gene's LOEUF score, 0.95, which puts it in group 4 of 6, group 1 being the genes least tolerant of losing a copy. Missense variants: 612 observed, 587.21 expected, observed/expected ratio (o/e) 1.04, 90% interval 0.98 to 1.11. Synonymous variants: 335 observed, 279.46 expected, observed/expected ratio (o/e) 1.2, 90% interval 1.1 to 1.31.
Gene-disease validity (ClinGen):
ClinGen rates the evidence that SLC52A2 causes each of these diseases.
Brown-Vialetto-van Laere syndrome 2 (autosomal recessive): Definitive.
Homologues: Orthologues: chimpanzee SLC52A2 (99% identical), macaque SLC52A2 (96% identical), dog SLC52A2 (84% identical), mouse Slc52a2 (83% identical), rat Slc52a2 (77% identical), zebrafish slc52a2 (51% identical), tropical clawed frog slc52a1 (50% identical), Drosophila melanogaster Rift (33% identical), Caenorhabditis elegans rft-1 (31% identical), Caenorhabditis elegans rft-2 (29% identical). Paralogues in human: SLC52A1 (86% identical), SLC52A3 (41% identical).